VDR (vitamin D receptor)
Diseases named in the same sentence as VDR in open-access papers (continued):
Sharing a sentence is not in itself a finding about the gene and the disease.
melanoma (continued). "Moreover, in lesions showing the most malignant phenotype, vertical growth phases, nodular histotype, and in primary melanomas with highest Clark level (V) and Breslow depth (≥3.1 mm) there was significant decrease or loss of VDR expression." (PMID 38927967, 2024). "Researchers examined multiple VDR gene polymorphisms in a study involving over 3600 individuals to identify that eight polymorphisms are statistically significantly associated with the risk of developing subsequent new primary melanomas." (PMID 38672780, 2024). "Loss of VDR expression has been correlated with melanoma progression." (PMID 35158770, 2022). "Over 600 single nucleotide polymorphisms have been identified in the VDR gene including FokI (C/T-rs2228570, previously named rs10735810), TaqI (rs731236), BsmI (rs1544410), and ApaI (rs7975232) which are the most commonly analyzed in relation to melanoma." (PMID 34692525, 2021). "This review discusses the role of VDR in the crosstalk between keratinocytes and melanocytes during melanomagenesis and summarizes the clinical data regarding VDR polymorphisms, VDR as a prognostic marker, and potential uses of vitamin D and its analogs as an adjuvant treatment for melanoma." (PMID 34692525, 2021). "The VDR is implicated in the regulation of an array of biological activities, including development and progression of cancer, for example breast, prostate and ovarian cancers and melanoma." (PMID 34206371, 2021). "VDR expression has been associated with melanoma malignancy." (PMID 34199802, 2021). "Furthermore, VDR genetic mutations correlate with an increased risk to incur in melanoma and with a graver prognosis." (PMID 33712642, 2021). "Overall, the understanding of VDR variants in melanoma remains poor." (PMID 32429485, 2020). "Recently, Muralidhar and colleagues analyzed 703 primary melanoma transcriptomes and found that high tumor VDR expression is associated with upregulation of pathways mediating antitumor immunity and downregulation of proliferative pathways, notably Wnt/β-catenin." (PMID 33227961, 2020). "Our study suggests a role for VDR polymorphisms in non-melanoma skin cancer development." (PMID 33255834, 2020). "A meta-analysis of six studies that investigated the association between five VDR polymorphisms (TaqI, FokI, BsmI, EcoRV, and Cdx2) and the risk of melanoma also showed that the Bsm1 genotype was associated with an increased risk of melanoma development." (PMID 30321335, 2019). "Several studies have looked at the association between VDR polymorphisms and melanoma." (PMID 30321335, 2019). "Frequent epigenetic and genetic alterations, such as single-nucleotide polymorphisms (SNPs), may increase or decrease the function of genes in VDR signaling pathways, resulting in susceptibility and modified prognosis of malignant melanoma." (PMID 29100280, 2017). "We then argued that there would be stronger evidence of causality if serum vitamin D levels at diagnosis were associated with less aggressive biological subtypes of melanoma, especially if the genes differentially expressed were in pathways known to be downstream of the vitamin D receptor." (PMID 27667313, 2016). "Moreover, exposure to UV light, particularly UVB, is a major environmental risk factor for melanoma, and VDR knockout mice developed melanoma more rapidly and with greater penetrance than did wild-type mice following UV exposure." (PMID 25887475, 2015). "Third, the method we employed did not take into account other co-factors such as age, sex, smoking, vitamin D level, or the latitude at which participants reside, all of which may modify the associations between specific VDR variants and melanoma risk." (PMID 25887475, 2015). "The VDR variants Fok1 and Bsm1 may influence the susceptibility to developing melanoma, though further studies are needed to verify these conclusions." (PMID 25887475, 2015).
melanoma (continued). "Following a systematic review and meta-analysis of relevant published epidemiological studies to date, we have identified that the VDR variants Bsm1 and Fok1 are associated with the risk of developing melanoma, while four other variants (Apa1, Cdx2, EcoRV, and Taq1) are not." (PMID 25887475, 2015). "Previous studies on human melanoma SKMEL-188 cells demonstrated that enhanced melanogenesis attenuated the antiproliferative activity of 20(OH)D3 which was associated with downregulation of VDR expression." (PMID 25811927, 2015). "In addition, certain polymorphisms of the VDR in humans have been associated with both melanoma susceptibility and Breslow thickness." (PMID 25563456, 2014). "The involvement of VDR in nevi and, in turn, in melanoma susceptibility has also been suggested." (PMID 23413917, 2013). "Although the significance of this association is not clear, the presence of this SNP among patients with light eye color could suggest the involvement of the VDR gene in melanoma predisposition among a subgroup of patients at risk of low 25-hydroxyvitamin D3." (PMID 23413917, 2013). "Furthermore, the association between VDR SNPs and nevus number, an established risk factor for melanoma, was also evaluated." (PMID 23413917, 2013). "In addition to the well-defined association of MC1R with melanoma, other low-penetrance melanoma risk alleles have been described in genes related to pigmentation, nevus count, immune responses, DNA repair, metabolism and the vitamin D receptor." (PMID 22978401, 2012). "However, studies examining the association between VDR SNPs and melanoma risk and prognosis are relatively rare compared to the other cancer types." (PMID 22576141, 2012). "However, other study showed opposite results: a significant association between the BsmI VDR polymorphism and increased melanoma risk (OR, 1.30, 95% CI, 1.11-1.53, the population attributable risk 9.2%)." (PMID 22759494, 2012). "Mainly VDR polymorphisms regarding melanoma risk and prognosis were examined although other vitamin D metabolism-related genes may also be crucial." (PMID 22576141, 2012). "These active forms regulate calcium metabolism and exhibit anticarcinogenic, anti-melanoma, and photoprotective effects, primarily via interactions with the vitamin D receptor (VDR) and retinoic acid orphan receptors (ROR)α and RORγ." (PMID 40177537, 2025). "Our results have shown that both siRIPK4 and CRISPR/Cas9-mediated RIPK4 knockout increase VDR expression in melanoma cells." (PMID 40490050, 2025). "Analysis of the TCGA-SKCM and GTEx datasets revealed elevated expression of NF2, SUZ39H1, CDC25A, GLRX5, and CISD3 in melanoma tissues, in contrast with the reduced expression of VDR, PPARD, CAMKK2, NT5DC2, and CHP1A." (PMID 40860143, 2025). "We observed a correlation between decreasing VDR expression and melanoma progression assessed according to pT stage." (PMID 38927967, 2024). "The defective VDR signaling in melanoma and its correlation with melanoma progression was also reviewed recently." (PMID 38927967, 2024). "It should be noted that VDR expression was affected by melanoma pigmentation and the lower VDR level was accompanied by melanin presence." (PMID 38927967, 2024). "With skin as the primary site of physiological vitamin D synthesis and a location of VDR expression, vitamin D homeostasis will likely have a profound effect on the development, treatment, and progression of melanoma." (PMID 38672780, 2024). "Studies in melanoma cells have shown that 1,25-(OH)2D3 inhibits the Wnt/β-catenin pathway and cell growth in vitro and in vivo, and that VDR expression was significantly upregulated post-treatment." (PMID 38666921, 2024). "An increase in the VDR protein level was also observed in A375 melanoma cells treated simultaneously with 1,25(OH)2D3 and CPL304110." (PMID 38473753, 2024).
melanoma (continued). "It has also been reported that ligand-induced VDR signaling can inhibit Wnt/β-catenin-mediated progression of melanoma and enhance antitumor immunity." (PMID 38927967, 2024). "A decreased expression of VDR in melanomas in comparison to benign melanocytic nevi was also reported by another group." (PMID 38927967, 2024). "1,25(OH)2D3 at pharmacological doses inhibited growth of VDR positive human melanoma xenografts in vivo, while being well tolerated when a low calcium diet was used." (PMID 38927967, 2024). "For the human WM164 melanoma these effects were partially dependent on the VDR as demonstrated in experiments with knocked down (KD) VDR vs. mock transfected cells (wild type: WT)." (PMID 38927967, 2024). "Other studies have shown that higher expression of VDR in melanoma represents a good prognostic factor." (PMID 38927967, 2024). "Knocking down VDR expression resulted in the enhanced proliferation of melanoma cells grown in 2D and 3D models and higher migration potential." (PMID 38927967, 2024). "The majority of the studies were performed on human melanoma cell lines and their growth inhibition by 1,25(OH)2D3 was dependent on VDR expression." (PMID 38927967, 2024). "There is mounting evidence that vitamin D supplementation has the potential to exhibit VDR-mediated anticancer properties in melanoma." (PMID 38672780, 2024). "Melanoma has been found to express VDR and respond to activities of active vitamin D, such as cell proliferation." (PMID 38672780, 2024). "In the present study, VDR overexpression decreased the mRNA and protein levels of β-catenin in vitro and in vivo, a finding that is consistent with previous findings in murine melanoma cells that elevated vitamin D-VDR levels inhibit Wnt/β-catenin signalling." (PMID 37046222, 2023). "An in silico virtual study demonstrated that the highest influential receptors in melanoma were the vitamin D receptor, CRH-R1, VEGFR 1, and c-Kit, which matches the results of experimental apoptotic and cell cycle analysis." (PMID 37631247, 2023). "Another study further explored the role of vitamin D signaling through the VDR in melanoma progression." (PMID 37892558, 2023). "Transcriptomes collected from patients with melanoma revealed that high VDR correlated with reduced cancer-related death in primary and metastatic disease and up-regulation of pathways conferring anti-tumor immunity." (PMID 37686465, 2023). "Higher levels of VDR expression were independently protective against melanoma-related death in both primary and metastatic diseases." (PMID 37892558, 2023). "Melanoma cell lines are responsive to the antiproliferative effect of vitamin D by expressing the vitamin D receptor." (PMID 36296975, 2022). "Vitamin D receptor (VDR) expression in malignant melanoma appears to be involved in the pathogenesis of malignant melanoma." (PMID 36358637, 2022). "IHC staining shows greater expression of VDR in unexposed site melanomas (such as vulvar) than in exposed ones." (PMID 36358637, 2022). "For example, epigenetic profiling of primary melanoma identified VDR hypermethylation important for melanoma progression and was associated with worse survival in a VDR-dependent manner." (PMID 36246903, 2022). "To further investigate this relationship, we knocked out the VDR gene in WM164 melanoma cells using CRISPR/Cas methodology as described in Materials and Methods." (PMID 34206371, 2021). "Further, high VDR expression both in primary and metastatic melanomas was a factor that favorably influenced the OS in melanoma cohort." (PMID 34692525, 2021). "For “cytoplasmic localization”, VDR expression decreased in the order: normal skin = melanocytic nevi > primary melanomas = metastases." (PMID 34692525, 2021). "Recently, there is evidence that points towards an inverse relationship with VDR expression and Wnt/β-catenin signaling in primary melanomas which yields reduced proliferation and immune response evasion." (PMID 34692525, 2021).
melanoma (continued). "VDR expression shows an inverse correlation with melanoma progression and poor outcome of the disease." (PMID 34206371, 2021). "Our studies demonstrating that knocking out VDR expression in human melanoma cells increases parameters of malignancy indicate that expression of VDR is connected with an increased malignant behavior in melanoma cells." (PMID 34206371, 2021). "One cohort-study assessed the relationship between VDR expression and prognostic factors in Central European cohort of melanoma patients." (PMID 34692525, 2021). "We observed that VDR mRNA level was elevated in A375 melanoma cells pretreated with vitamin D and subsequently incubated with cediranib at 1,000 nM concentration (p < 0.05)." (PMID 35004285, 2021). "They found that VDR expression was independently protective against melanoma-related death in both primary and metastatic disease." (PMID 34692525, 2021). "Of note, melanogenesis can stimulate HIF1α expression and anaerobic glycolysis in melanoma cells explaining in part the correlation between defects in VDR expression and signaling and defective responses to vitamin D in pigmented melanoma cells." (PMID 34692525, 2021). "The strongest expression of VDR was observed in normal skin, and its expression decreased from normal skin through melanocytic nevi and melanoma to metastases." (PMID 34206371, 2021). "They found that as melanomas progressed, they exhibited reduced nuclear localization of VDR and increased cytoplasmic localization." (PMID 34692525, 2021). "Most importantly patients with metastatic disease and VDR-/- melanomas had the poorest probability of survival." (PMID 34692525, 2021). "The strongest expression of VDR was observed in normal skin, which decreased during progression of melanocytic lesions and during melanoma development." (PMID 34206371, 2021). "Previous clinicopathological studies have shown an inverse correlation between VDR expression, melanoma progression and poor outcome of the disease." (PMID 34206371, 2021). "In order to explore the role of the VDR in melanoma cells in more depth, we established a melanoma cell line with the expression of the VDR knocked out and compared this to control cells with a functional VDR." (PMID 34206371, 2021). "Daily cell counting using a hemocytometric chamber and daily measurements of the space occupied by the cells confirmed that knocking out the VDR in WM164 melanoma cells accelerates their multiplication rate." (PMID 34206371, 2021). "Subsequent experiments using human melanoma cell lines confirmed that the VDR is present in melanoma cells, although its expression level was heterogeneous between different cell lines." (PMID 34206371, 2021). "Reduction in VDR expression with the development of the pigmented lesions was more evident in the nuclei than in the cell-cytoplasm suggesting a cell-autonomous role of canonical VDR signaling in the melanocytes during melanoma progression and metastasis." (PMID 34692525, 2021). "Our results indicate that VDR expression affects the characteristics of the melanoma line originally derived from human skin." (PMID 34206371, 2021). "For “nuclear localization”, VDR expression decreased in the following order: normal skin > melanocytic nevi > primary melanomas = metastases." (PMID 34692525, 2021). "VDR expression has been shown to be negatively correlated with overall prognosis in melanoma patients, painting an important picture for vitamin D-based therapy." (PMID 32429485, 2020). "A comparable cytoplasmic staining pattern of VDR was noticed in malignant melanoma, colon and vulvar cancer affecting tumor progression and prognosis." (PMID 32572587, 2020). "PD and melanoma both have vitamin D insufficiency, and a lower expression level of VDR was found in melanoma." (PMID 32210791, 2020).
melanoma (continued). "It was also shown that melanogenesis induction in human SKMel-188 melanoma cells was accompanied by a marked decrease in VDR expression and responsiveness to active forms of vitamin D26,68." (PMID 31235702, 2019). "In our study we confirmed the presence of CYP27B1 and CYP24A1 in the melanoma cells and their connection with the VDR level." (PMID 31235702, 2019). "A relationship between sun exposure and VDR genotypes was evaluated in a case-control study in melanoma survivors." (PMID 30321335, 2019). "The treatment of A375 melanoma with four vitamin D3 analogs (1,25(OH)2D3, calcipotriol and 21(OH)pD) decreased the expression of VDR, RXR, PDIA3, CYP2R1 genes." (PMID 30200275, 2018). "In melanoma cell lines, VDR mediates the repression of TNF-α-induced IL-8 promoter activity by calcitriol." (PMID 29865262, 2018). "We have analyzed the antiproliferative potential of analogs and found that 21(OH)pD inhibits melanoma growth through a mechanism independent from VDR or PDIA3." (PMID 30200275, 2018). "Our previous studies have indicated that the inhibition of melanoma proliferation by a short side-chain, low calcemic analog of vitamin D—21(OH)pD is not fully dependent on the expression of vitamin D receptor (VDR)." (PMID 30200275, 2018). "In this context, it must be noted that clinic-pathological studies have shown a correlation between changes in the expression of VDR or RORs with melanoma progression and also with overall and disease free survival time of the patients." (PMID 28039464, 2017). "These processes are possibly being mediated through the expression of VDR in malignant melanoma cells and primary melanoma tissue." (PMID 28835228, 2017). "The relative involvement of the VDR or RORα and γ in the inhibition of melanoma growth by 20(OH)D3 represents a challenging goal for future investigation." (PMID 28039464, 2017). "Previously, we have demonstrated that 20(OH)D3 and its metabolites can inhibit NF-κB signaling through an interaction with VDR in keratinocytes and melanoma cells." (PMID 28039464, 2017). "A lower VDR expression, at the same time, was observed in melanoma especially for the vertical growth phase versus normal skin or nevi and hypo-activation of VDR signaling pathway can inhibit melanocytic progression." (PMID 29100280, 2017). "Our study aimed to examine the associations between the clinical outcomes of malignant melanoma and some variants of SNPs in PIK3CA, PIK3R1 and VDR genes." (PMID 29100280, 2017). "In this study, we have investigated the capacity of our series of (DPM) analogs of 1,25-dihydroxyvitamin D2 to inhibit cell proliferation of the human malignant melanoma VDR positive A375 and VDR depleted SK-MEL 188b cell lines." (PMID 26760999, 2016). "Post-treatment of A375 melanoma with 1,25(OH)2D3, expression of VDR was inhibited slightly, while CYP24A1, the vitamin D catabolic enzyme, was strongly induced." (PMID 26760999, 2016). "A similar finding has been reported from studies of murine melanoma cell lines, in which pigmentation increased the expression of VDR and CYP24A1 at the mRNA level, and of SK-MEL 188 human melanoma cells." (PMID 26760999, 2016). "This is consistent with our previous observation showing the reduction of OS and DFS of patients with a pigmented melanomas at stage 3 and 4, and on expression of several vitamin D related pathways such as VDR, CYP24A1 and CYP27B1 and HIF-1α." (PMID 27542227, 2016). "Previously we demonstrated that expression of nuclear receptor for vitamin D (VDR) in melanomas decreased with tumor progression." (PMID 27542227, 2016). "We have already tested the in vitro activity of the major product of this pathway, 20(OH)D3, and its metabolites, finding that they show antiproliferative activity against cultured melanoma cells, acting as biased agonists on the VDR." (PMID 25811927, 2015).